HSF4 (heat shock transcription factor 4)
Diseases named in the same sentence as HSF4 in open-access papers (continued):
Sharing a sentence is not in itself a finding about the gene and the disease.
tumor (continued). "The results showed that HSF4 knockout significantly reduced the number of liver metastases and, combined with LOXL1 overexpression, further decreased the number of metastatic tumours in the liver." (PMID 39881364, 2025). "This study reveals that tumour stiffness promotes the proliferation and metastasis of CRC by regulating EMT-related signalling pathways through HSF4." (PMID 39881364, 2025). "Our findings underscore the critical role of tumour stiffness and ECM mechanics in CRC progression and suggest that HSF4 is a potential therapeutic target." (PMID 39881364, 2025). "Importantly, HSF4 promotes CRC growth and metastasis independently of collagen content, highlighting the complex interactions between tumour cells and their microenvironment." (PMID 39881364, 2025). "In vivo experiments confirmed that HSF4 promoted tumour growth and metastasis, independent of collagen protein increase." (PMID 39881364, 2025). "These discoveries underscore the central role of the mechanical properties of the tumour microenvironment in CRC progression and highlight the potential of HSF4 as a therapeutic target, paving the way for new strategies in CRC prevention, diagnosis, and treatment." (PMID 39881364, 2025). "Notably, HSF1, HSF2, and HSF4 were upregulated in HCC, KIRP, and COAD, with HSF1 being upregulated in most tumor types." (PMID 39248163, 2024). "As a key member of the heat shock transcription factor family, HSF4 may indirectly affect the characteristics of the tumour microenvironment by regulating downstream target genes, thereby enhancing tumour stiffness and malignancy without directly increasing collagen content." (PMID 39881364, 2025).
genetic diseases (1 paper, 2010). "Taking into account previous studies showing genetic and mutation homogeneity of genetic diseases in Tunisia, the splice variation (c.1327+4A-G) in the HSF4 gene previously identified in one Tunisian family with an autosomal recessive cataract was screened in individuals with MdM and cataract." (PMID 20406438, 2010).
infection (1 paper, 2015). The state of being infected such as from the introduction of a foreign agent such as serum, vaccine, antigenic substance or organism. "Finally, we also observed a higher susceptibility of Hsf 4 mutants to IIV-6 infection compared to wild-type flies (P < 0.001), whereas the Hsf rescue line remained at wild-type levels." (PMID 26234525, 2015). "Upon DCV challenge, Hsf 4 mutants succumbed faster to infection than wild-type flies (mean survival = 2.2 and 5.5 days, respectively; P < 0.001)." (PMID 26234525, 2015). "In order to establish whether the heat shock response is important for antiviral defence, or merely a secondary effect of infection-induced stress, we challenged Hsf 4 mutant flies with several viruses and monitored survival over time." (PMID 26234525, 2015). "However, we noted that Hsf 4 mutants also had a reduced life span in mock infections." (PMID 26234525, 2015).
HSF4 also shares sentences with these, for which no sentence is quoted: esophageal squamous cell carcinoma (2 papers); Alzheimer disease (1); Anterior polar cataract (1); colon adenocarcinoma (1); coronary artery disease (1); diabetes mellitus (1); digestive system carcinoma (1); episodic ataxia (1); glioma (1); glomerulonephritis (1); heart failure (1); liver cancer (1); lung carcinoma (1); lymphoma (1); osteoporosis (1); ovarian carcinoma (1); renal cell carcinoma (1); uterine carcinosarcoma (1).